ABLIM1 (actin binding LIM protein 1)
Description:
May act as scaffold protein (By similarity). May play a role in the development of the retina. Has been suggested to play a role in axon guidance.
Synonyms: abLIM-1; ABLIM; LIMAB1; limatin
Tractability: PROTAC: UniProt records ubiquitination sites on it; ubiquitination databases record sites on it; its protein half-life has been measured.
Gene: Protein-coding gene on chromosome 10 (114,431,110 to 114,768,061, reverse strand). Ensembl gene ENSG00000099204.
Subcellular location: Cytoplasm; Cytoplasm, cytoskeleton
Subcellular location (Human Protein Atlas): Cytosol; Connecting piece; Mid piece
Pathways (Reactome):
Developmental Biology: DCC mediated attractive signaling
Gene Ontology:
Molecular function: protein binding; actin binding; actin filament binding
Biological process: cilium assembly; lamellipodium assembly; animal organ morphogenesis; visual perception; cytoskeleton organization
Cellular component: lamellipodium; stress fiber; actin cytoskeleton; cytoplasm; cytoskeleton; postsynaptic density
Genetic constraint (gnomAD): Loss-of-function variants: 39 observed, 98.93 expected, observed/expected ratio (o/e) 0.39, 90% interval 0.3 to 0.51. The upper end of that interval is the gene's LOEUF score, 0.51, which puts it in group 2 of 6, group 1 being the genes least tolerant of losing a copy. Missense variants: 812 observed, 987.59 expected, observed/expected ratio (o/e) 0.82, 90% interval 0.77 to 0.87. Synonymous variants: 328 observed, 346.27 expected, observed/expected ratio (o/e) 0.95, 90% interval 0.87 to 1.04.
Homologues: Orthologues: chimpanzee ABLIM1 (99% identical), guinea pig ABLIM1 (93% identical), dog ABLIM1 (93% identical), pig ABLIM1 (93% identical), rabbit ABLIM1 (92% identical), rat AABR07007032.1 (91% identical), macaque ABLIM1 (90% identical), mouse Ablim1 (86% identical), tropical clawed frog ablim1 (75% identical), zebrafish ablim1a (64% identical), zebrafish ablim1b (37% identical), Drosophila melanogaster Unc-115a (32% identical), and 1 more. Paralogues in human: ABLIM3 (47% identical), ABLIM2 (45% identical), DMTN (24% identical).
Diseases named in the same sentence as ABLIM1 in open-access papers:
ABLIM1 is named in the same sentence as 35 diseases in open-access papers, as found by Europe PMC text mining. Sharing a sentence is not in itself a finding about the gene and the disease. The quoted sentences say what the papers report.
nasopharyngeal carcinoma (6 papers, 2020 to 2025). A carcinoma arising from the nasopharyngeal epithelium. "A few studies reveal low levels and a tumor suppressor role of ABLIM1 in melanoma, nasopharyngeal carcinoma, and glioblastoma; however, the underlying mechanisms governing ABLIM-mediated tumorigenesis remain elusive." (PMID 41409245, 2025). "Several studies investigated its low expression profiles in glioblastoma and declared ABLIM1 might act as a tumor suppressor in glioblastoma, nasopharyngeal carcinoma, and melanoma, however the underlying mechanism remains unclear." (PMID 38228802, 2024). "The lncRNA ZNF667-AS1 promoted ABLIM1 expression by adsorbing miR-1290, subsequently attenuating nasopharyngeal carcinoma progression." (PMID 36583064, 2022). "The tumor-related role of ABLIM1 has also been reported in hepatocellular and nasopharyngeal carcinoma." (PMID 36583064, 2022). "Functionally, the overexpression of ZNF667-AS1 was shown to suppress the proliferation of nasopharyngeal carcinoma cells via increasing the ABLIM1 expression via adsorbing miR-1290." (PMID 33282010, 2020). "Cancers like melanoma, nasopharyngeal carcinoma, and glioblastoma may lack specific cofactors required for IκBα ubiquitination, limiting ABLIM1’s E3 ligase function." (PMID 41409245, 2025).
colorectal cancer (5 papers, 2024 to 2025). A primary or metastatic malignant neoplasm that affects the colon or rectum. "For instance, the E3 ligase ABLIM1 is upregulated in colorectal cancer and promotes tumor growth and metastasis through activation of the NF-κB signaling pathway." (PMID 40280416, 2025). "Enhanced ABLIM1 mRNA expression in colorectal cancers was observed in both freshly frozen CRC samples in our cohort and the GEO datasets (GSE20916 and GSE5206)." (PMID 38228802, 2024). "Most studies on the function of ABLIM1 focused on its role in regulating actin networks, whereas its role and corresponding mechanism in cancers, especially colorectal cancer, remains rarely known." (PMID 38228802, 2024). "To grasp the expression profile of ABLIM1 in human colorectal cancer, we investigated its mRNA and protein expression levels in freshly frozen CRC samples, paraffin-embedded tissue microarray, human colorectal cell lines, and GEO database." (PMID 38228802, 2024). "In colorectal cancer (CRC), ABLIM1 has been identified as an oncogenic factor, promoting tumor growth and metastasis through the activation of the NF-ĸB signaling pathway." (PMID 40831931, 2025). "Interestingly, ABLIM1 has been previously reported to be down-regulated and act as a candidate tumor suppressor in glioblastoma and melanoma, whereas its expression pattern and role remain unknown in colorectal cancers." (PMID 38228802, 2024). "Actin-binding LIM protein 1 (ABLIM1), a member of the LIM-domain protein family, has been reported as a suppressor in several tumors whereas its role in colorectal cancer (CRC) remains unknown." (PMID 38228802, 2024). "Additionally, mRNA expression levels of RELA in colorectal cancers and normal colorectal tissues from the GEPIA2 database were positively correlated with those of ABLIM1, supporting the regulation of ABLIM1 on p65." (PMID 38228802, 2024).
hepatocellular carcinoma (5 papers, 2020 to 2025). A malignant tumor that arises from hepatocytes. "Rictor mediates the phosphorylation of the actin-binding LIM protein 1 (ABLIM1) in hepatocellular carcinoma." (PMID 38270460, 2024). "The major finding is the upregulation of ABLIM1 in cholangiocarcinoma compared to hepatocellular carcinoma, colorectal liver metastases, pancreatic ductal adenocarcinoma liver metastases and healthy liver tissue." (PMID 39766812, 2024). "Besides its total protein expression level, ABLIM1 phosphorylation has been previously reported to participate in hepatocellular carcinoma (HCC) progression." (PMID 36583064, 2022). "In hepatocellular carcinoma (HCC), ABLIM1 is involved in actin polymerization and cell migration, processes crucial for cancer metastasis." (PMID 40831931, 2025).
glioblastoma (4 papers, 2022 to 2025). The most malignant astrocytic tumor (WHO grade IV). "In contrast, in glioblastoma (GBM), ABLIM1 acts as a tumor suppressor, where its overexpression is associated with reduced tumor size and improved patient survival, implicating the diverse role of ABLIM1 in different cancer context." (PMID 40831931, 2025). "Here, we found ABLIM1 exhibited a distinct expression profile (highly expressed in CRCs compared with adjacent normal counterparts) in CRC than in glioblastoma and high ABLIM1 expression predicted a short DFS time, indicating a different role of ABLIM1 in CRC." (PMID 38228802, 2024).
liver cancer (2 papers, 2020 to 2024). An epithelial or non-epithelial malignant neoplasm that arises from the liver. "The data from the cBioPortal database demonstrated that the frequency of genetic alterations of ABLIM1 in liver cancer accounted for approximately 0.4~0.8%, including mutations." (PMID 33061800, 2020). "This strong differential expression of ABLIM1 indicates it to be a promising candidate as a biomarker for differentiating CCA from both primary liver cancers and metastatic liver cancers." (PMID 39766812, 2024).
alcohol (1 paper, 2018). "Only one genome-wide association study has been performed so far and identified the ABLIM1 gene of relevance for novelty seeking, harm avoidance and reward dependence in alcohol-dependent patients." (PMID 28054193, 2018).
astrocytoma (1 paper, 2022). "ABLIM1 level comparison based on histological types revealed that GBM has the lowest ABLIM1 level than astrocytoma or oligodendroglioma (P < 0.001)." (PMID 36583064, 2022).
cardiac hypertrophy (1 paper, 2022). "We found that lncRNA Airn, lncRNA Ttc4, lncRNA Ablim1 and lncRNA Nav3 were novel lncRNAs associated with cardiac hypertrophy." (PMID 35402096, 2022).
cholangiocarcinoma (1 paper, 2024). A carcinoma that arises from the intrahepatic biliary tree (intrahepatic cholangiocarcinoma) or from the junction, or adjacent to the junction, of the right and left hepatic ducts (hilar cholangiocarcinoma). "We propose ABLIM1 as a potential biomarker that differentiates cholangiocarcinoma from other cancers and healthy liver tissue." (PMID 39766812, 2024).
colon carcinoma (1 paper, 2024). "ABLIM1 was up-regulated in multiple colon carcinoma cell lines, including HCT116, SW480, SW620, and Lovo, when compared with the normal colon epithelial cell line, HCoEpic." (PMID 38228802, 2024).
colorectal tumor (1 paper, 2024). "Data in the GEPIA 2 database indicated ABLIM1 expression was reduced in 17 types of tumors but enhanced in colorectal tumor and 3 other tumors." (PMID 38228802, 2024).
COVID-19 (1 paper, 2021). A disease caused by infection with severe acute respiratory syndrome coronavirus 2. "Both, severe and mild COVID-19 in comparison to controls shared neutrophil-specific CD177 and HP expression among the most upregulated DEGs, as well as lymphocyte-associated genes such as ABLIM1, NELL2, RCAN3, RORC, BACH2, and KLRB1, among the downregulated genes." (PMID 33441124, 2021).
glaucoma (1 paper, 2016). Increased pressure in the eyeball due to obstruction of the outflow of aqueous humor. "Specifically, the ABLIM1 gene is related to changes in the actin cytoskeleton and is associated with POAG and steroid‐induced glaucoma via cytoskeletal changes in trabecular meshwork cells." (PMID 27386793, 2016).
glioma (1 paper, 2022). A benign or malignant brain and spinal cord tumor that arises from glial cells (astrocytes, oligodendrocytes, ependymal cells). "GBM tissues (WHO grade IV) had significantly lower ABLIM1 levels than low-grade gliomas (WHO grade II-III)." (PMID 36583064, 2022). "ABLIM1 exhibited a significantly lower mRNA level in GBM than in other glioma or normal brain tissues." (PMID 36583064, 2022). "We investigated ABLIM1's detailed role in GBM due to its significantly lower level than other glioma types." (PMID 36583064, 2022). "We discovered that ABLIM1 exhibits distinct levels in glioma tissues with different WHO grades by extracting the microarray data from the TCGA database." (PMID 36583064, 2022). "Notably, glioma patients with a lower ABLIM1 level had shorter overall survival than those with a higher ABLIM1 level (P < 0.001)." (PMID 36583064, 2022).
mesothelioma (1 paper, 2025). A usually malignant and aggressive neoplasm of the mesothelium which is often associated with exposure to asbestos. "In kidney renal clear cell carcinoma (KIRC) and Mesothelioma (MESO), high expression of ABLIM1 was significantly associated with better prognosis." (PMID 40831931, 2025).
multiple sclerosis (1 paper, 2019). A progressive autoimmune disorder affecting the central nervous system resulting in demyelination. "Importantly, altered allelic expression of two imprinted genes (ZNF331 and GNAS) and five non-imprinted genes (ABLIM1, UBE2I, KIAA1267, CD6, and ATHL1) were detected between the multiple sclerosis discordant co-twins." (PMID 31850058, 2019).
pneumonia (1 paper, 2024). An acute, acute and chronic, or chronic inflammation focally or diffusely affecting the lung parenchyma, caused by an infection in one or both of the lungs (by bacteria, viruses, fungi, or mycoplasma.). "The results showed significantly higher levels of OLAH, HPGD, and LY96 in sepsis patients compared to those with preoperative conditions or pneumonia, increased by 95.16-, 6.58-, and 2.89-fold, respectively, while ABLIM1 was downregulated by 7.33-fold." (PMID 39628572, 2024).
prion disease (1 paper, 2026). A transmissible disease that is caused by a protein that is able to induce abnormal folding of normal cellular proteins, leading to characteristic spongiform brain changes, which are associated with neuronal loss without an inflammatory response. "RNA-seq analysis revealed that hypothalamic CYTB, ATP6, COX, ABLIM1, and ABI3 were significantly upregulated in IM group, whereas SHISA7 and PTPRO were significantly downregulated, with notable enrichment in prion disease, oxidative phosphorylation, and thermogenesis pathways." (PMID 41715947, 2026).
sarcoma (1 paper, 2022). A usually aggressive malignant neoplasm of the soft tissue or bone. "In other previous studies, some genes (CCND1, CD109, NOS1, and ABLIM1) were found to be abnormally expressed in sarcomas, which can be used as prognostic markers or classification features for different sarcomas." (PMID 36619306, 2022).
Sepsis (1 paper, 2024). Sepsis is defined as life-threatening organ dysfunction caused by a dysregulated host response to infection. "The refined model, comprising genes OLAH, LY96, HPGD, and ABLIM1, demonstrated high predictive accuracy for 28-day mortality and excelled in early sepsis detection." (PMID 39628572, 2024).
Stroke (1 paper, 2025). Sudden impairment of blood flow to a part of the brain due to occlusion or rupture of an artery to the brain. "Nine days post-stroke, proteins annotated as thin filaments were upregulated, including Ablim1, Dbnl, Parvb, Capg, and Pdlim3; Actn2, Pdlim7, Tpm1, and cofilin 2 (Cfl2) were downregulated." (PMID 41226396, 2025). "Six days post-stroke, differentially expressed thin filament proteins were annotated as follows: Ablim1, Pdlim1, Lmod2, Dbnl, Parvb, Pdlim3, Tpm2, parvin alpha (Parva), and destrin (Dstn) were upregulated, while Lmod3 was downregulated." (PMID 41226396, 2025).
Usher syndrome (1 paper, 2025). A syndromic diseae characterized by the association of sensorineural deafness (usually congenital) with retinitis pigmentosa and progressive vision loss. "Several genes, such as IGHV1-69D, CTSH, and LMO7, exhibited significant upregulation in Usher syndrome, while others, including SLC3A2, ABLIM1, and CBS, were notably downregulated." (PMID 40723835, 2025).
uterine tumor (1 paper, 2025). "Our study showed that ABLIM1 was broadly downregulated in uterine tumor samples, indicating a possible protective role during the transformation of uterine smooth muscle cells." (PMID 40831931, 2025).
ZIKV infection (1 paper, 2020). "Along the same lines, levels of ABLIM1, an actin-binding protein, were reduced by ZIKV infection by 24 hpi, despite its increase at later time points." (PMID 32850779, 2020).
cancer (13 papers, 2016 to 2025). A tumor composed of atypical neoplastic, often pleomorphic cells that invade other tissues. "Further, investigating the mutational status of ABLIM1 in CRC could help to identify genetic alterations that underlie its cancer-specific regulatory mechanisms." (PMID 41409245, 2025). "Interestingly, many of the DMGs identified had multiple roles and several were potential cancer biomarkers or were previously shown to be implicated in various types of cancers, including ABLIM1, ADAM12, ARHGEF4, FBLN2, ITGA6, LRPAP1, Ly9, NT5E, PITPNC1, PLCG1, OBSCN, RHOH, SPTBN1, SPOCK2 and SPRY1." (PMID 41159936, 2025). "The first question revolves around the dual nature of ABLIM1 in cancer- how does this protein serve both tumor-suppressive and promoting functions, and what molecular mechanisms underlie this duality?" (PMID 41409245, 2025). "Our most important finding is the significantly higher expression of ABLIM1 compared to healthy liver tissue and other cancers." (PMID 39766812, 2024). "Taking an overview of the different cancers, we can see that ABLIM1 is downregulated in the majority of other cancers, including HCC, which is consistent with our experimental results." (PMID 39766812, 2024). "Analysis from our phosphoproteomics data showed that phosphorylation of ABLIM1 at serine residues was decreased when Rictor was downregulated in cancer cell lines." (PMID 33061800, 2020). "We also found a number of genes whose expression follows this pattern: high-grade cancers < low-grade cancers < normal tissue, such as ALDH1L1, WIF1, ACSL1, FOS, and ABLIM1 in at least four cancer types." (PMID 28427185, 2017). "These included several candidate tumor suppressor genes, such as ABLIM1, CYFIP2, VPS13A, SERPINI1, TET2, HTRA4, UBE2L6, as well as oncogenes/genes implicated as biomarkers in other cancers, such as FAM65B and TCF7L2." (PMID 27385100, 2016). "Combination therapy targeting both ABLIM1 and the NF-ĸB pathway might give better anti-cancer therapeutic options." (PMID 41409245, 2025). "It is possible that ABLIM1 binds different substrates or partners in different cancer types." (PMID 41409245, 2025). "The role of ABLIM1 in cancer is controversial and cancer type dependent." (PMID 40831931, 2025). "Similar to ABLIM1, it has been reported to play dual role in cancer dependent on cancer type." (PMID 40831931, 2025). "Structurally, LIM-domain proteins contain one or more Zn-finger motifs that are like really interesting new gene (RING) and thus are predicted to possess E3 ligase activities, though the functions of most of them in cancers, including ABLIM1, remain unclear." (PMID 38228802, 2024). "ABLIM1 maps to human chromosome 10q25, a frequently deleted region in human cancers." (PMID 36583064, 2022). "In contrast to TOP2A, the remaining three genes—ABLIM1, FHL5, and MAP3K8—exhibit more context-dependent roles in cancers." (PMID 40831931, 2025). "Higher ABLIM1 protein level was correlated with smaller GBM tumor size and better cancer-specific survival (CSS)." (PMID 36583064, 2022). "Furthermore, using in vitro and in vivo studies, the authors showed that ABLIM1 functions as an oncogene to promote the growth and liver metastasis of CRC cells, unlike its previously reported tumor suppressive role in other cancer models." (PMID 41409245, 2025). "Among them, ephrin receptor EPHA4, actin binding LIM-proteins ABLIM1 and ABLIM2, semaphorin SEMA7A and glial neurotrophic factor GFRA2 genes, which are involved in axon guidance, are commonly repressed in cancer cells by DiPRO1 and SIX1." (PMID 39009887, 2024).